NUDT3 (nudix hydrolase 3)
Description:
Cleaves a beta-phosphate from the diphosphate groups in PP-InsP5 (diphosphoinositol pentakisphosphate) and [PP]2-InsP4 (bisdiphosphoinositol tetrakisphosphate), suggesting that it may play a role in signal transduction. InsP6 (inositol hexakisphosphate) is not a substrate. Acts as a negative regulator of the ERK1/2 pathway (By similarity). Also able to catalyze the hydrolysis of dinucleoside oligophosphates, with diadenosine 5',5'''-P1,P6-hexaphosphate (Ap6A) and diadenosine 5',5'''-P1,P5-pentaphosphate (Ap5A) being the preferred substrates. The major reaction products are ADP and p4a from Ap6A and ADP and ATP from Ap5A. Also able to hydrolyze 5-phosphoribose 1-diphosphate. Acts as a decapping enzyme that modulates the stability of a subset of mRNAs implicated in cell motility. Hydrolyzes monomethylated capped RNA after both the alpha- and beta-phosphates generating m7GMP + ppRNA and m7GDP + pRNA. Can hydrolyze unmethylated capped RNAs (By similarity). Divalent cations zinc, magnesium and manganese determine its substrate specificity. Exhibits diphosphoinositol polyphosphate phosphohydrolase in the presence of magnesium ions, diadenosine hexaphosphate hydrolase activity in the presence of manganese ions and endopolyphosphatase activity in the presence of zinc ions. Plays an important role in limiting DNA damage and maintaining cell survival upon oxidative stress via its endopolyphosphatase activity.
Synonyms: DIPP-1; DIPP; DIPP1
Tractability: Small molecule: a structure with a bound ligand is known. PROTAC: its protein half-life has been measured.
Target class: Enzyme; Hydrolase
Gene: Protein-coding gene on chromosome 6 (34,279,679 to 34,392,677, reverse strand). Ensembl gene ENSG00000272325.
Subcellular location: Cytoplasm; Nucleus
Subcellular location (Human Protein Atlas): Cytosol
Pathways (Reactome):
Metabolism: Synthesis of pyrophosphates in the cytosol
Gene Ontology:
Molecular function: 5'-(N(7)-methyl 5'-triphosphoguanosine)-[mRNA] diphosphatase activity; 5'-(N(7)-methylguanosine 5'-triphospho)-[mRNA] hydrolase activity; diphosphoinositol-polyphosphate diphosphatase activity; endopolyphosphatase activity; inositol diphosphate pentakisphosphate diphosphatase activity; inositol diphosphate tetrakisphosphate diphosphatase activity; inositol-3,5-bisdiphosphate-2,3,4,6-tetrakisphosphate 5-diphosphatase activity; inositol-5-diphosphate-1,2,3,4,6-pentakisphosphate diphosphatase activity; magnesium ion binding; manganese ion binding; protein binding; zinc ion binding; bis(5'-adenosyl)-hexaphosphatase activity; bis(5'-adenosyl)-pentaphosphatase activity; hydrolase activity; pyrophosphatase activity
Biological process: diadenosine hexaphosphate catabolic process; diphosphoinositol polyphosphate catabolic process; RNA decapping; adenosine 5'-(hexahydrogen pentaphosphate) catabolic process; cell-cell signaling; diadenosine pentaphosphate catabolic process; diadenosine polyphosphate catabolic process; diphosphoinositol polyphosphate metabolic process
Cellular component: cytoplasm; nucleus; cytosol; glutamatergic synapse; synapse
Genetic constraint (gnomAD): Loss-of-function variants: 9 observed, 23.12 expected, observed/expected ratio (o/e) 0.39, 90% interval 0.23 to 0.68. The upper end of that interval is the gene's LOEUF score, 0.68, which puts it in group 2 of 6, group 1 being the genes least tolerant of losing a copy. Missense variants: 172 observed, 219.04 expected, observed/expected ratio (o/e) 0.79, 90% interval 0.69 to 0.89. Synonymous variants: 86 observed, 83.15 expected, observed/expected ratio (o/e) 1.03, 90% interval 0.87 to 1.24.
Homologues: Orthologues: chimpanzee NUDT3 (100% identical), dog NUDT3 (99% identical), pig NUDT3 (99% identical), mouse Nudt3 (95% identical), rat Nudt3 (95% identical), zebrafish nudt3b (84% identical), zebrafish nudt3a (84% identical), guinea pig NUDT3 (80% identical), rabbit NUDT3 (55% identical). Paralogues in human: NUDT4 (76% identical), NUDT4B (76% identical), NUDT11 (71% identical), NUDT10 (70% identical).
Diseases named in the same sentence as NUDT3 in open-access papers:
NUDT3 is named in the same sentence as 21 diseases in open-access papers, as found by Europe PMC text mining. Sharing a sentence is not in itself a finding about the gene and the disease. The quoted sentences say what the papers report.
Obesity (7 papers, 2015 to 2023). Accumulation of substantial excess body fat. "In an epigenetic association study, researchers found that Etv5, Nudt3, Wwox, Zeb1, and Maf DNA methylation alterations were related to obesity in peripheral blood leukocytes of humans." (PMID 35458198, 2022). "The Malacards database also associates NUDT3 with hyperinsulinism and obesity in specific populations." (PMID 32093658, 2020). "Many studies proved that NUDT3 is the obesity-linked gene for human, Drosophila, and mouse, possibly because of its polymorphic activity against polyphosphate substrates." (PMID 31188900, 2019). "NUDT3, SPDEF, and PACSIN1 have been identified in a closely linked region that is associated with obesity or carcass traits, such as body growth and size, in human or pigs." (PMID 31188900, 2019). "The homolog of NUDT3 in Drosophila, Aps, is involved in insulin signaling, while defects in PACSIN1 have been associated with schizophrenia-like behavior in mice, another condition linked to obesity." (PMID 37620670, 2023). "In ConvR HFD mice liver, 17 genes DNA methylation changes including Ube2l3, Etv5, Lrp1, and Nudt3 were determined related to obesity and 11 genes DNA methylation changes including Exoc312, Mst1r, Prkch, and Arhgap26 were determined related to Type 2 diabetes (T2D) in the previous study." (PMID 35458198, 2022). "Instead, our screen suggests that different nearby cis gene may be more fruitful for further functional follow up for obesity, namely ZCCHC8, VPS33A, RSRC2; SPDEF, NUDT3; SETD1, VKORC1; SGSM2, SRR; VASP, SIX5; OTX1; BANK1; ARIH1; ELL; CHST8, respectively." (PMID 29608557, 2018).
sarcopenia (5 papers, 2020 to 2024). Progressive decline in muscle mass due to aging which results in decreased functional capacity of muscles. "The NUDT3 gene and myogenin expression have proven efficient as diagnostic tools for sarcopenia." (PMID 38684784, 2024). "Evaluating NUDT3 gene and myogenin expression as new diagnostic tools in sarcopenia." (PMID 38684784, 2024). "Recent studies have found that, in humans, the interacting protein NUDT3 of QPCTL is an important genetic biomarker of sarcopenia in elderly individuals." (PMID 36552455, 2022). "A genome-wide association study on Korean cohorts showed that ribosomal protein S10 (RPS10), nudix hydrolase 3 (NUDT3), and glycerol-3-phosphate dehydrogenase 1 like (GPD1L) are genetic biomarkers of age-related sarcopenia." (PMID 39457696, 2024). "The eQTL analysis for muscle mass using GTEx datasets showed that RPS10, NUDT3, NCF2, SMG7, and ARPC5 were differentially expressed in the muscle tissue for sarcopenia." (PMID 35241739, 2022). "This study aimed to investigate the NUDT3 gene which has not been studied before, myogenin expression as evaluation tools and to identify new treatment approaches for delaying age-related sarcopenia." (PMID 38684784, 2024). "Our study identified RPS10, NUDT3, and GPD1L as significant genetic biomarkers for sarcopenia." (PMID 35241739, 2022).
breast carcinoma (3 papers, 2021 to 2023). "The results showed that 17 m7GRGs were risk factors and significantly impacted breast cancer prognosis, whereas NUDT10, NUDT3, EIF4E3, SNUPN, NUDT16, IFIT5 and EIF3D were favourable prognostic factors." (PMID 37353728, 2023). "As another example, scLink identified an edge between EGR1 and NUDT3 in the normal sample (scLink’s correlation = − 0.48, adjusted P = 0.004) but not in the tumor sample (scLink’s correlation = 0.35), and both genes were reported to have regulatory roles in breast cancer." (PMID 34252628, 2021). "It is found that through genome-wide and NUDT3 gene knockout cell analysis of NUDT3 damaged cells, NUDT3 is a mRNA dissociation enzyme that directly or indirectly affects the stability of mRNAs and regulates expression levels to adjust the cell migration, such as MCF-7 breast cancer cell migration." (PMID 36335189, 2022).
type 2 diabetes (2 papers, 2017 to 2023). "While genomic variations in the CCDC102A locus were found to be associated with diabetic cataract, polymorphisms at the NUDT3 locus were associated with body mass index (BMI), adiposity and pediatric onset type 2 diabetes." (PMID 38093359, 2023).
endometrial stromal tumor (1 paper, 2024). Neoplasms of the endometrial stroma that sometimes involve the myometrium. "RAD51B::NUDT3 fusion should be added to the spectrum of fusions which may occur in uterine leiomyoma, which can be of value especially in cellular leiomyoma in the context of differential diagnosis against endometrial stromal tumors." (PMID 37466765, 2024).
epilepsy (1 paper, 2025). A brain disorder characterized by episodes of abnormally increased neuronal discharge resulting in transient episodes of sensory or motor neurological dysfunction, or psychic dysfunction. "In this work, we screened five key m7G regulators in epilepsy and created a nomogram based on them to predict the risk of epilepsy, including METTL1, NUDT3, EIF4E3, LSM1, and SNUPN." (PMID 40658715, 2025). "The boxplot revealed that epilepsy patients had up-regulated expression levels of NUDT3, EIF4E3, LARP1, IFIT5, and SNUPN, and down-regulated expression levels of METTL1, EIF4A1, and LSM1." (PMID 40658715, 2025). "Gene expression analysis of datasets GSE143272 and GSE190452 identified 8 differentially expressed m7G regulators (NUDT3, EIF4E3, LARP1, IFIT5, SNUPN, METTL1, EIF4A1, and LSM1) in epilepsy." (PMID 40658715, 2025).
hepatocellular carcinoma (1 paper, 2022). A malignant tumor that arises from hepatocytes. "The Kaplan–Meier survival curve showed that the patients with hepatocellular carcinoma in the high-risk group and those with NSUN2, NUDT3 and LARP1 genes in the high expression group had a lower survival rate and shorter survival time." (PMID 36335189, 2022).
leiomyoma (1 paper, 2024). A well-circumscribed benign smooth muscle neoplasm characterized by the presence of spindle cells with cigar-shaped nuclei, interlacing fascicles, and a whorled pattern. "In our study, we described two cases of uterine leiomyoma with RAD51B::NUDT3 fusion, which occur in one case of usual-type and one case of cellular leiomyoma." (PMID 37466765, 2024). "The results of our study showed that RAD51::NUDT3 fusion can occur in both usual and cellular leiomyoma." (PMID 37466765, 2024). "In our study, we described two cases of uterine leiomyoma with RAD51B::NUDT3 fusion, which occur in one case of usual and one case of highly cellular leiomyoma." (PMID 37466765, 2024). "In conclusion, our study showed that RAD51::NUDT3 fusion can occur in both usual and cellular leiomyoma." (PMID 37466765, 2024). "RAD51B may be a fusion partner of HMGA2 and HMGA1 but can occur in fusion with other genes including NUDT3 and seems to be a potential driver event in these tumors mutually exclusive with other driver aberrations defining molecular leiomyoma subtypes." (PMID 37466765, 2024). "Another study comparing uterine leiomyoma and leiomyosarcoma found that a small percentage (3 out of 56) of leiomyoma cases showed a RAD51B fusion (with HMGA2, NCOR2, and NUDT3), and one of these cases with RAD51B::NUDT3 fusion is reported here in detail." (PMID 37466765, 2024).
prostate carcinoma (1 paper, 2015). A carcinoma that arises from epithelial cells of the prostate gland. "For instance, the gene NUDT3 is not yet reported in relation to prostate cancer, but NUDT3 participates in the Collagen biosynthesis and modifying enzymes pathway which has been identified as a prostate cancer related pathway." (PMID 26106884, 2015).
uterine sarcoma (1 paper, 2025). "RAD51B fusion uterine sarcoma is not a morphological diagnosis, but rather a mixture of recently recognized subset of uterine sarcomas characterized by gene fusions involving RAD51B and various partner genes, most commonly HMGA2 or NUDT3." (PMID 41463261, 2025).
tumor (11 papers, 2019 to 2025). "In addition, we found that ZEB1-AS1 and NUDT3 were linked to B cell and macrophage infiltration in our research, which may promote tumor immunosuppression." (PMID 35794981, 2022). "Notably, DCPS manifested pronounced expression in both neoplastic and non‐neoplastic tissues, while DCP2, NCBP2, WDR4, and NUDT3 demonstrated intermediate expression across tumor and normal samples." (PMID 40485623, 2025). "Interestingly, we noted that NUDT3, as a Nudix protein possessing mRNA-decapping activity in cells, was upregulated in tumor tissues of LUAD (|log2FC| = 0.4 and p < 0.001), but its high expression predicted significantly better survival." (PMID 35785179, 2022). "Moreover, as the biomarkers for tumor immunity, the potential function of NUDT3 and ZEB1-AS1 in tumor immunity is still unclear, which needs further research." (PMID 35794981, 2022). "For example, decapping enzyme Nudt3, a member of nudix hydrolase superfamily, promoting MCF7 cell migration and proliferation by modulating β6 and lipocalin-2 mRNA stability; Dcp2, the first discovered decapping enzyme, enhanced tumor cell growth by affected RAS and MYC mRNA stability." (PMID 31164795, 2019).
NUDT3 also shares sentences with these, for which no sentence is quoted: cancer (3 papers); schizophrenia (2); endometrial carcinoma (1); glioma (1); hyperinsulinism (1); inflammatory myofibroblastic tumor (1); leiomyosarcoma (1); melanoma (1); Pituitary adenoma (1); Uterine leiomyoma (1).